GSTP1 (glutathione S-transferase pi 1)
Diseases named in the same sentence as GSTP1 in open-access papers (continued):
Sharing a sentence is not in itself a finding about the gene and the disease.
autism spectrum disorder (5 papers, 2016 to 2024). A spectrum of developmental disorders that includes autism, and Asperger syndrome. "There is evidence that the GSTP1 polymorphism is associated with several neurological conditions, such as multiple sclerosis and autism spectrum disorders." (PMID 36851015, 2023). "However, in children heterozygous for the GSTP1 Ile105Val polymorphism, the odds of autism spectrum disorders were significantly higher in those with the null GSTT1 genotype than those with the other genotypes." (PMID 31357662, 2019). "Interestingly, the role of GSTP1, GST theta 1, and GST mu 1 gene polymorphisms in susceptibility to autism spectrum disorders was investigated." (PMID 31357662, 2019). "We investigated interactive roles of three metabolic glutathione S-transferase (GST) genes (GSTP1, GSTT1, and GSTM1) and autism spectrum disorder (ASD) status in relation to blood Hg concentrations (BHC) of Jamaican children." (PMID 33546147, 2021). "In this respect, studies were recently carried out about the correlation between autism spectrum disorders and detoxifying enzymes (like GST and in particular GSTP1)." (PMID 31357662, 2019).
liver fibrosis (5 papers, 2015 to 2023). "Consequently, CR led to an elevation of proteomic markers associated with liver inflammation (e.g., GSTP1, GPX3) or liver fibrosis (e.g., TGFBI, TNC), and therefore, rather compromised liver health instead of improving it." (PMID 37630850, 2023).
myelodysplastic syndrome (5 papers, 2020 to 2024). A clonal hematopoietic disorder characterized by dysplasia and ineffective hematopoiesis in one or more of the hematopoietic cell lines. "Telintra (TLK199) is a small-molecule GSTP-1 inhibitor being investigated as a potential preventive treatment for myelosuppression in blood diseases, namely myelodysplastic syndrome." (PMID 38256132, 2024). "Notably, a GSTP1 inhibitor, Ezatiostat, has passed phase-II clinical trials for treating myelodysplastic syndrome, indicating that GSTP1 inhibitors might be used for human cancers." (PMID 33087132, 2020). "A potent GSTP1 inhibitor, TLK199 (Telik Inc.), has been shown to modulate cell proliferation in human myeloid leukemic cells and is under clinical trial for myelodysplastic syndrome." (PMID 32526885, 2020). "Furthermore, we explored the therapeutic potentials of pharmacological inhibition of GSTP1 by using a GSTP1 inhibitor ezatiostat, an FDA‐approved drug for myelodysplastic syndromes." (PMID 36709476, 2023).
oesophageal cancer (5 papers, 2010 to 2022). "The variation in the impact of GSTM1, GSTT1 and GSTP1 in oesophageal cancer susceptibility could be due to their differences in organ localization and metabolic functions." (PMID 20540773, 2010). "Genetic polymorphisms in genes involved in detoxification such as glutathione-S-transferases (GST), GSTM1, GSTT1 and GSTP1 could potentially affect the susceptibility of an individual to the adverse effects of environmental risk factors involved in oesophageal cancer." (PMID 21134244, 2010). "PDxK and GSTP1 expressions have been previously correlated to resistance to platinum-based chemotherapy in ovarian and esophageal carcinomas." (PMID 35565353, 2022). "We have earlier reported a significant increase in the risk of oesophageal cancers correlated with the null genotypes of GSTM1 and GSTT1 but not with the GSTP1 Ile/Val polymorphism." (PMID 21134244, 2010).
oral cancer (5 papers, 2012 to 2023). "Individuals with the GSTP1 AA-genotype showed association with the oral cancer (OR = 3.1, 95% CI = 2.4–4.2, p = 0.0002)." (PMID 32265484, 2020). "The present data demonstrate that GSTP1 AA-genotype is significantly associated with the oral cancer in cases compared to controls (Dominant model; OR = 3.1, 95% CI = 2.4–4.2, p-value = 0.0002)." (PMID 32265484, 2020). "The present study confirms that the AA homozygous genotype of GSTP1 gene is significantly associated with the risk of oral cancer even after adjusting for age, gender and habit of RAN/tobacco usage in the population." (PMID 32265484, 2020). "Our results are consistent with those of Hashibe and colleagues, except the finding of the higher risk of oral cancer than the risk of laryngeal cancer for the GSTP1 any valine genotype." (PMID 23144854, 2012). "Thus, chronic exposure to tobacco in combination with the GSTP1 AA genotype increases the risk of developing oral cancer through accumulation of DNA lesions and lower phosphorylation of c-Jun, which controls apoptosis." (PMID 37886736, 2023). "Thus, habit of using RAN/tobacco and GSTP1 AA-genotype together play a significant role in predisposition to oral cancer risk by showing higher DNA-lesions and lower c-Jun phosphorylation that may inhibit apoptosis." (PMID 32265484, 2020). "We found that a combination of six genes (TP73, CASP8, RARB, KLLN, GSTP1, and CHFR) could distinguish oral cancer from clinically diagnosed OPMDs with high diagnostic performance (area under the curve [AUC], 0.885; sensitivity, 77.8%; and specificity, 87.1%)." (PMID 35681626, 2022). "We have explored the association of GSTP1 (A313G) (rs1695) with the risk of oral cancer in the people chewing RAN with and without tobacco." (PMID 32265484, 2020). "The GSTP1 AA reference allele (rs1695) is significantly associated with the risk of oral cancer to those having RAN consumption habit with and without tobacco." (PMID 32265484, 2020). "The role of GSTP1 polymorphism (A313G; Ile105Val) as a susceptibility factor in oral cancer was evaluated in a hospital-based case-control study in North-East India, because the habit of chewing raw areca-nut (RAN) with/without tobacco is common in this region." (PMID 32265484, 2020). "Evaluation of the combination of six genes with aberrant methylation (RARB, KLLN, CHFR, TP73, GSTP1, and CASP8) was particularly useful for identifying early-stage oral cancer in clinically diagnosed patients with OPMDs with high diagnostic performance." (PMID 35681626, 2022). "Materials and Methods: Forty-eight subjects answered the Fagerström, and AUDIT tests and we studied them as likely screening tools for oral cancer and their correlation with the expression of CYP1A1, GSTM1, GSTP1, and GSTT1 genes by the RT-qPCR method." (PMID 35409669, 2022).
schizophrenia (5 papers, 2015 to 2025). A major psychotic disorder characterized by abnormalities in the perception or expression of reality. "We found associations of polymorphic variants rs1695 and rs614080 of the GSTP1 gene with metabolic buildups in patients with schizophrenia." (PMID 40732231, 2025). "We found statistically significant differences in the frequencies of rs1695 alleles (χ2 = 5.87; p = 0.015) in the GSTP1 between normal and obese schizophrenia patients." (PMID 40732231, 2025). "We found statistically significant differences in the frequencies of rs1695 genotypes (χ2 = 13.793; p = 0.001) and alleles (χ2 = 4.976; p = 0.026) in the GSTP1 between normal and overweight schizophrenia patients." (PMID 40732231, 2025). "The rs1695 variant of the GSTP1 is significantly associated with the BMI of schizophrenia patients receiving antipsychotic therapy." (PMID 40732231, 2025). "Overall analysis between polymorphisms of glutathione S-transferase genes (GSTM1, GSTT1, and GSTP1) and susceptibility of schizophrenia." (PMID 26295386, 2015). "These polymorphisms of GSTM1, GSTT1, and GSTP1 have been investigated with various diseases including schizophrenia, hypertension, and capacity for oxidation and detoxification." (PMID 26295386, 2015). "Therefore, we performed a meta-analysis on all eligible case-control studies to clarify the association between the GSTM1, GSTT1, and GSTP1 polymorphisms and risk of schizophrenia." (PMID 26295386, 2015). "Therefore, we performed a meta-analysis to explore the association between the GSTM1, GSTT1, and GSTP1 polymorphisms and the risk of schizophrenia." (PMID 26295386, 2015). "We found statistically significant differences in the frequencies of rs1695 genotypes in the GSTP1 between normal and overweight schizophrenia patients (χ2 = 6.749, p = 0.034)." (PMID 40732231, 2025). "The present study investigated the possible associations between three polymorphisms in GSTP1 and GSTO1 genes and the risk of overweight and MetS in patients with schizophrenia." (PMID 40732231, 2025). "Our results support the hypothesis that antioxidant status is impaired, particularly with regard to the role of the GSTP1 gene in antipsychotic-induced metabolic disorders in schizophrenia." (PMID 40732231, 2025). "Our meta-analysis results revealed that GSTM1, GSTT1, and GSTP1 polymorphisms were not related to risk of schizophrenia (p > 0.05 in each model)." (PMID 26295386, 2015). "GSTP1 polymorphisms do not confer susceptibility to schizophrenia." (PMID 31357662, 2019). "GSTM1 polymorphism was associated with susceptibility to schizophrenia in only East Asian population and GSTT1 and GSTP1 polymorphisms did not related to schizophrenia." (PMID 26295386, 2015).
autoimmune disease (4 papers, 2020 to 2025). A disorder resulting from loss of function or tissue destruction of an organ or multiple organs, arising from humoral or cellular immune responses of the individual to their own tissue constituents. "Indeed, studies have demonstrated a significant association between the allelic variation GSTP1 Ile105Val and disease remissions dependent on cyclophosphamide treatment in patients with various autoimmune diseases, including vasculitis." (PMID 39063019, 2024).
endothelial dysfunction (4 papers, 2019 to 2025). In vascular diseases, endothelial dysfunction is a systemic pathological state of the endothelium (the inner lining of blood vessels) and can be broadly defined as an imbalance between vasodilating and vasoconstricting substances produced by (or acting on) the endothelium. "As such, GSTP1 polymorphic variants may determine individual susceptibility to oxidative stress, inflammation, and endothelial dysfunction in HF, as well." (PMID 31275451, 2019). "In conclusion, GSTP1 polymorphic variants may determine individual susceptibility to oxidative stress, inflammation, and endothelial dysfunction in HF." (PMID 31275451, 2019). "GSTP1 has been shown in mice to protect against vessel endothelial dysfunction induced by environmental toxins by detoxifying relevant electrophilic compounds." (PMID 40722932, 2025). "Separately, our computational predictions and experimental work implicate LGALS8 and GSTP1 as crucial effectors of endothelial dysfunction in PH." (PMID 34669463, 2021). "To take further insight into molecular mechanisms and potential consequences of GSTP1 and GSTA1 polymorphisms with respect to CAD-related HF, we correlated the GSTP1 and GSTA1 variant genotypes with both the indices of heart remodeling and parameters of endothelial dysfunction." (PMID 31275451, 2019).
gynecological cancer (4 papers, 2017 to 2024). "In the past decade, several case-control studies about the relationship between the GSTP1 Ile105Val polymorphism and gynecological cancer susceptibility have been conducted." (PMID 28410197, 2017). "The association between the glutathione S-transferase P1 (GSTP1) Ile105Val polymorphism and gynecological cancer susceptibility has been evaluated in many studies." (PMID 28410197, 2017). "Therefore, we performed the present meta-analysis using data from 10 previously published case-control studies to more precisely assess the association between the GSTP1 Ile105Val polymorphism and gynecological cancer risk." (PMID 28410197, 2017). "Thus, this meta-analysis, based on 10 published case-control studies, was designed to clarify the association of the GSTP1 Ile105Val polymorphism with gynecological cancer risk." (PMID 28410197, 2017). "Biochemical studies have indicated that the GSTP1/Val105 variant is 2-3 times less stable than the Ile105 variant and may be associated with the risk of gynecological cancers." (PMID 28410197, 2017). "Perhaps worth to mention is a comprehensive pharmacogenomic analysis in 320 gynecological cancers patients, of which GSTP1 rs1695 showed the lowest p-value against severe hematological toxicity (p = 0.00034)." (PMID 39234108, 2024). "The results of our meta-analysis did not indicate any significant association between the GSTP1 Ile105Val polymorphism and the risk of gynecological cancer, both in the overall study population and in the stratified subgroup analyses." (PMID 28410197, 2017).
head and neck squamous cell carcinoma (4 papers, 2012 to 2024). A squamous cell carcinoma that arises from any of the following anatomic sites: lip and oral cavity, nasal cavity, paranasal sinuses, pharynx, larynx, and salivary glands. "For example, GSTP1 was found to serve as an oncogene that suppresses cell apoptosis in head and neck squamous cell carcinoma, while another study showed that inhibition of GSTP1 expression promoted EC chemoresistance to 5-FU." (PMID 38540273, 2024). "Recently, miR-133a, a cognate molecule of miR-133b, was reported to regulate the expression of GSTP1 in head and neck squamous cell carcinoma (HNSCC) cells." (PMID 22532850, 2012).
Hearing impairment (4 papers, 2007 to 2023). A decreased magnitude of the sensory perception of sound. "A deletion of 3 nucleotides on GSTM3 gene has been shown to have a protective role, whereas having GSTT1 and GSTM1 genes and the A/A genotype at rs1695 in GSTP1 has been associated with hearing loss." (PMID 30112115, 2018). "We showed that 3 of them, rs1695 in GSTP1, the absence of GSTT1, and rs1799793 in XPD/ERCC2 were significantly associated with hearing impairment, whereas rs4880, rs2228001, rs4788863, rs1799735, and presence of GSTM1 were not." (PMID 30112115, 2018). "However, in the present study GSTP1-GG did not protect against self-reported hearing impairment." (PMID 18162130, 2007).
Hypertension (4 papers, 2014 to 2023). The presence of chronic increased pressure in the systemic arterial system. "This study's main findings are an association between indicators of long-term vehicle exhaust exposure and acute myocardial infarction, and an effect for several variants in the GSTP1 gene on risk of hypertension." (PMID 24915237, 2014). "Three GSTP1 SNPs were significantly associated with hypertension." (PMID 24915237, 2014). "This study shows significant association of vehicle air pollution exposure with risk of AMI; effects of variants in the GSTP1 gene on risk of hypertension, and suggests interactions between variants in the GSTP1, GSTT1 and GSTCD genes and vehicle air pollution exposure on risk of AMI." (PMID 24915237, 2014). "In contrast, 5 of the 7 GSTP1 SNPs had a p-value≤0.05 for hypertension; the 3 strongest of these (rs1871042, rs749174 and rs762803) remained significant after Bonferroni-correction (p-value≤0.007)." (PMID 24915237, 2014). "Effects of the most significant variants in GSTP1, the GSTCD SNP rs10516526 (dominant genetic model) and the GSTT1 SNP rs2266637 (null genotype) on risk of acute myocardial infarction (AMI) and hypertension." (PMID 24915237, 2014). "We aimed to investigate effects of long-term traffic-related air pollution exposure, as well as variants in GSTP1, GSTT1 and GSTCD, on risk of acute myocardial infarction (AMI) and hypertension." (PMID 24915237, 2014).
lung disease (4 papers, 2017 to 2023). "Previous studies suggest that ADRB2, GNB3, TH, and GSTP1 polymorphisms are associated with various lung diseases." (PMID 28212552, 2017). "As previously discussed, GSTP1 might modulate the susceptibility to various pulmonary diseases." (PMID 35361071, 2022). "Another lung disease in which GSTP1 inhibition is suggested as a novel therapeutic strategy is lung fibrosis, since GSTP1 is an important participant in protein S-glutathionylation." (PMID 34988113, 2021).
meningioma (4 papers, 2015 to 2022). A generally slow growing tumor attached to the dura mater. "Comparing our two main histologic groups, we found both GSTM and GSTP1 expressed more strongly in meningiomas than in astrocytomas, both at gene and protein level." (PMID 26580399, 2015). "The different statistical analysis shows interesting interrelations between apoptotic genes and autophagy, and a surprising involvement of GSTP1, BCL2 DAPK1, and HIC1 that deserves further consideration in meningioma." (PMID 36011000, 2022). "Promoter methylation of MEG3, GSTP1, and MAL2 has been shown to more commonly in higher grade meningiomas." (PMID 33194703, 2020).
myocardial infarction (4 papers, 2011 to 2019). Gross necrosis of the myocardium, as a result of interruption of the blood supply to the area, as in coronary thrombosis. "Interestingly, the same authors indicated that a single dose of recombinant GSTP1 has cardioprotective effect in rats after myocardial infarction, affecting both inflammatory and apoptotic responses." (PMID 31275451, 2019). "The effect of GSTM1, GSTT1, GSTP1 and GSTA1 gene polymorphisms on predicting overall and specific cardiovascular outcomes (myocardial infarction, MI or stroke) was analyzed using Cox regression model, and differences in survival were determined by Kaplan-Meier." (PMID 24423050, 2014). "This study examined the association between the deletion polymorphisms in GSTM1 and GSTT1 as well as SNPs in GSTA1 (rs3957357) and GSTP1 (rs1695) genes with overall and cardiovascular mortality as well as the death from myocardial infarction (MI) and stroke (CVI) in 199 dialysis patients." (PMID 24423050, 2014). "There were no robust statistical associations between GSTP1 and GSTT1 gene variants with overall, cardiovascular mortality as well as the death of myocardial infarction and stroke in dialysis patients according to Cox regression analysis." (PMID 24423050, 2014).
osteoporosis (4 papers, 2014 to 2024). A condition of reduced bone mass, with decreased cortical thickness and a decrease in the number and size of the trabeculae of cancellous bone (but normal chemical composition), resulting in increased fracture incidence. "The GSTT1 deletion was associated with a higher frequency of the NMPA to homozygous deletion (p = 0.008), GSTP1 + 313A > G with a minor risk of osteoporosis (p = 0.036), and patient age ≤ 154 months (p = 0.044) with the AA genotype." (PMID 24593045, 2014). "Five GMs, including GSTP1, TNF-α, TNF-β (LT-α), SLC6A14, and S1P, were associated with the musculoskeletal system and an increased risk of osteoporosis and reduced bone density." (PMID 40225935, 2024). "Chromosome QTL 11q12-13, where the GSTP1 gene is located, has been associated with variation of bone mineral density (BMD) and osteoporosis-pseudoglioma syndrome, a disorder affecting skeletal strength and vision." (PMID 26046522, 2015). "Finally, we screened four candidate proteins of osteoporosis with iron accumulation, GSTP1, LAMP2, COPB1, and RAB5B." (PMID 36313751, 2022). "We ultimately identified 4 core proteins (GSTP1, LAMP2, COPB1, RAB5B) that were significantly differentially expressed in the bone of osteoporosis patients with iron accumulation, and validated the changed protein level in the serum of the medical examination population." (PMID 36313751, 2022). "Together, these 4 core proteins (GSTP1, LAMP2, COPB1, and RAB5B) may account for osteoporosis with iron accumulation, and potentially be a serum marker for it." (PMID 36313751, 2022). "Therefore, we speculate that these 4 DEPs (GSTP1, LAMP2, COPB1, RAB5B) may be novel candidate core proteins of osteoporosis with iron accumulation." (PMID 36313751, 2022).